ANGPTL4 (angiopoietin like 4)
Diseases named in the same sentence as ANGPTL4 in open-access papers (continued):
Sharing a sentence is not in itself a finding about the gene and the disease.
cervical tumor (1 paper, 2022). "Expression analysis in TCGA (The Cancer Genome Atlas) revealed that FSCN1 had negative correlations with several transcription factors and a positive correlation with an angiogenic factor (angiopoietin like 4, ANGPTL4) in cervical tumor tissue." (PMID 35178306, 2022).
chronic gastritis (1 paper, 2024). Inflammation of the stomach that is chronic in nature. "Importantly, our results together identify a multi-step model of persistent H. pylori infection accompanied with chronic gastritis involving cross-talks between H. pylori, IL-17A, GECs, ANGPTL4, neutrophils, monocytes, as well as Tregs." (PMID 39022746, 2024).
colorectal adenocarcinoma (1 paper, 2025). The most common type of colorectal carcinoma. "Previous studies have shown that ANGPTL4 expression is weak in normal colorectal tissue; however, more than 50% of human colorectal adenocarcinoma samples display positive staining for ANGPTL4." (PMID 40723247, 2025).
coronary stenosis (1 paper, 2021). Narrowing of the coronary artery lumen diameter. "The plasma ANGPTL3 level was higher (51.71 ± 52.67 vs. 24.65 ± 10.32 ng/mL, P < 0.001) and that of ANGPTL4 was lower (454.66 ± 269.05 vs. 875.49 ± 961.15 ng/mL, P < 0.001) in the coronary artery stenosis ≥ 10% group than in the < 10% group." (PMID 34742313, 2021). "The plasma ANGPTL3 level was higher and that of ANGPTL4 lower in the coronary stenosis > 10% group than in the nonstenosis group." (PMID 34742313, 2021).
Crohn disease (1 paper, 2018). A gastrointestinal disorder characterized by chronic inflammation involving all layers of the intestinal wall, noncaseating granulomas affecting the intestinal wall and regional lymph nodes, and transmural fibrosis. "For instance, PTVs in CARD9, RNF186 and IL23R provide protection against Crohn’s disease and/or ulcerative colitis and PTVs in ANGPTL4, PCSK9, LPA, and APOC3 protect against coronary heart disease." (PMID 29691392, 2018).
energy metabolism disorders (1 paper, 2018). "Although FGF21 and ANGPTL4 have important roles in the adaptation of energy metabolism, these two hepatokines may be involved in the pathological processes of energy metabolism disorders during the peripartum period in dairy cows." (PMID 30103741, 2018). "Although FGF21 and ANGPTL4 could play important roles in the adaptation of energy metabolism, they may be involved in the pathological processes of energy metabolism disorders of dairy cows in the peripartum period." (PMID 30103741, 2018). "However, as far as we know, no relevant studies have assessed changes in serum ANGPTL4 levels in dairy cows with energy metabolism disorders." (PMID 30103741, 2018). "In addition to our interest in whether ANGPTL4 and FGF21 participate in the pathological process of energy metabolic disorders in cows, we hypothesized that the serum concentration of these two hepatokines in dairy cows with ketosis and fatty liver are different from the contemporary healthy cows." (PMID 30103741, 2018). "According to our results, we speculate that upregulation of FGF21 and ANGPTL4 due to NEB could diminish adipose tissue insulin sensitivity and further aggravate lipolysis during early lactation in dairy cows, thus playing a role in the pathological processes of energy metabolism disorders." (PMID 30103741, 2018).
esophageal disease (1 paper, 2013). "In addition, serum ANGPTL4 level in ESCC patients was much higher than that in patients with benign esophageal disease (P < 0.001), and area under the curve was 0.94 (95 % CI 0.886390–0.978173, P < 0.001)." (PMID 23925665, 2013).
gastric adenocarcinoma (1 paper, 2025). "In vitro, COL1A1 overexpression in HUVECs increased ANGPTL4, and co-culture with the gastric adenocarcinoma line MKN45 enhanced cancer cell invasion and proliferation, supporting a model in which ANGPTL4 from COL1A1+ ECs engages SDC4 on tumor cells to promote GC progression and spread." (PMID 41154806, 2025).
gastric diseases (1 paper, 2024). "Moreover, CLDN1 expression was negatively correlated with ANGPTL4 within the H. pylori-infected gastric mucosa of patients and mice along with higher ANGPTL4 in patients with gastric ulcer, suggesting potential roles of gastric mucosal damage of ANGPTL4 in H. pylori-associated gastric diseases." (PMID 39022746, 2024).
gastritis (1 paper, 2024). Inflammation of the stomach. "To investigate the involvement of ANGPTL4 in H. pylori-associated pathology, we first enrolled 2 public datasets of clinic samples of gastritis associated with H. pylori infection from the Gene Expression Omnibus (GEO) (GSE60427 and GSE60662)." (PMID 39022746, 2024). "Third, within the gastric mucosa, higher ANGPTL4 protein levels of H. pylori-infected patients were strongly associated with more severe gastritis, indicating that, during H. pylori infection, ANGPTL4 might exert roles of promoting inflammation." (PMID 39022746, 2024). "In the current study, we have, for the first time, demonstrated a pathological role for ANGPTL4 in gastric H. pylori persistence and H. pylori infection-induced clinical gastritis." (PMID 39022746, 2024). "Overall, we propose a model in which ANGPTL4 collectively ensures H. pylori persistence and promotes gastritis." (PMID 39022746, 2024). "In turn, ANGPTL4 induced Treg proliferation by binding to ITGAV to activate PI3K–AKT–NF-κB, promoting H. pylori-associated gastritis." (PMID 39022746, 2024). "Human gastric ANGPTL4 correlated with H. pylori colonization and the severity of gastritis, and mouse ANGPTL4 from non-bone marrow-derived cells promoted bacteria colonization and inflammation." (PMID 39022746, 2024). "First, within the gastric mucosa of patients infected with H. pylori, positive correlations between ANGPTL4 and CCL5 as well as between CCL5 and Foxp3 were found, and CCL5 was also increased and was found to be positively correlated with the severity of gastritis." (PMID 39022746, 2024).
glomerulonephritis (1 paper, 2014). A renal disorder characterized by damage in the glomeruli. "In human glomerulonephritis, glomerular Angptl4 expression and urine Angptl4 excretion were clearly increased in MN and MCD patients but not in non-podocytopathy MsPGN patients, indicating that Angptl4 may be related to podocyte injury in humans." (PMID 25165975, 2014).
granular cell carcinoma (1 paper, 2024). An adenocarcinoma characterized by the presence of malignant epithelial cells with granular cytoplasm. "We found that the expression of ANGPTL4 was significantly increased in benign ovarian disease (ovarian mucinous cystadenoma and teratoma) and OC (ovarian serous cystadenocarcinoma and granular cell carcinoma) compared to normal ovary samples and corresponding para-carcinoma tissue samples." (PMID 38212795, 2024).
hemorrhage (1 paper, 2020). Loss of blood from the vascular compartment to the exterior or into nonvascular body space as a result of rupture or severance of the blood vessels. "The same effects were obtained through the use of recombinant human angiopoietin-like protein 4 (ANGPTL4), which contrasts the no reflow phenomenon and the intra-myocardial hemorrhage." (PMID 33143256, 2020).
hepatitis C (1 paper, 2021). "Firstly, we characterised the expression patterns of the host lipid regulatory factors ANGPTL-3 and ANGPTL-4 throughout the natural course of hepatitis C in vivo and HCV infection in vitro." (PMID 34360721, 2021). "The present study mainly determined the serum levels of the host lipid regulators ANGPTL-3 and ANGPTL-4 in HCV patients throughout the natural history of hepatitis C, from acute infection to HCC." (PMID 34360721, 2021). "In conclusion, we investigated, for the first time, ANGPTL-3 and ANGPTL-4 expression throughout the natural history of hepatitis C in vivo and long-term HCV infection in vitro and then determined the corresponding ANGPTL levels after treatment with DAAs." (PMID 34360721, 2021).
hyperuricemia (1 paper, 2022). An abnormally high level of uric acid. "Large-scale prospective studies investigating the association between hyperuricemia and ANGPTL4 are required to replicate our findings." (PMID 35711366, 2022). "However, we incidentally found that serum ANGPTL4 levels were independently correlated with TRL-C levels, especially in subjects with hyperuricemia." (PMID 35711366, 2022).
hypothyroidism (1 paper, 2022). Abnormally low levels of thyroid hormone. "For instance, two clinical trials found that the LOF mutation of ANGPTL4 gene was closely associated with decreased serum TG levels and increased HDL-C levels, whereas another study demonstrated ANGPTL4 could not significantly modulated the serum TG concentrations in patients with hypothyroidism." (PMID 34784265, 2022).
hypoxia (1 paper, 2023). A decrease in the amount of oxygen in the body. "To further assess whether the reduced glycolytic phenotype observed upon ANGPTL4 KD was, at least in part, dependent on its secretion from ECs, we incubated control or ANGPTL4 KD ECs in conditioned media (CM) enriched (NS-Hypoxia CM) or depleted of ANGPTL4 (siANGPTL4-Hypoxia CM)." (PMID 38086791, 2023).
infantile hemangiomas (1 paper, 2023). "Angiogenic factors such as ANGPTL4 are also upregulated in infantile hemangiomas and their expression can be suppressed with the drug propranolol, or more specifically, the stereoisomer R-propranolol." (PMID 36902020, 2023).
intervertebral disc degeneration (1 paper, 2021). "The aim of the current study is to investigate the role of ANGPTL4 in intervertebral disc degeneration and analyze the association of ANGPTL4 expression with Pfirrmann grades." (PMID 34876931, 2021). "The results demonstrated that ANGPTL4 expression was positively associated with the Pfirrmann grades and the severity of intervertebral disc degeneration." (PMID 34876931, 2021). "ANGPTL4 may be served as a candidate biomarker for intervertebral disc degeneration." (PMID 34876931, 2021).
invasive breast carcinoma (1 paper, 2022). A carcinoma that infiltrates the breast parenchyma. "However, the chi-square test did not detect a significant association between ANGPTL4 expression and specific molecular subtypes of invasive breast carcinoma in young women (p = 0.897)." (PMID 35366286, 2022).
keloid (1 paper, 2017). An irregularly shaped, elevated mark on the skin caused by deposits of excessive amounts of collagen during wound healing. "Whether ANGPTL4 plays a role in these fibrotic diseases, such as keloids, cardiac and corneal fibrosis, infarct scar formation remains to be determined." (PMID 28740178, 2017).
kidney tumor (1 paper, 2023). "The other 3 genes in the prognosis model associated with lipid metabolism regulation displayed the diagnostic potential to discriminate between normal and kidney tumor tissues: ACAT1, ANGPTL4 and ACAA2." (PMID 36829161, 2023). "Using IHC data from the Protein atlas database, we observed strong or moderate staining for ACAA2, ACAT1, ASRGL1, and AKR1B10, weak staining for ANGPTL4 and ABCC2 in normal kidney tissues and opposite staining results in kidney tumor samples." (PMID 36829161, 2023).
liposarcoma (1 paper, 2026). A usually painless malignant tumor that arises from adipose tissue. "Nevertheless, Koff and colleagues recently reported that ANGPTL4 contributes to the resistance of liposarcoma cells to CDK4/6 inhibitors, potentially by mitigating senescence features." (PMID 41347893, 2026).
liver disease (1 paper, 2021). "Therefore, we investigated the putative effect of DAA administration on the serum concentration of ANGPTL-3 and ANGPTL-4, in clinical samples from various stages of HCV-induced liver disease." (PMID 34360721, 2021).
lumbar disc degeneration (1 paper, 2024). "Some genes are widespread in chondrocyte 4, and chondrocyte 5 may play an important role in the process of lumbar disc degeneration together with the Wnt/Ca2+signaling pathway, such as ANGPTL4, PTGES, IGFBP3, GDF15, TRIB3, and TNFRSF10B." (PMID 38654287, 2024). "ANGPTL4, IGFBP3, PTGES in chondrocytes 4 and TRIB3, GDF15, TNFRSF10B in chondrocytes 5 may play an important role in the lumbar disc degeneration process." (PMID 38654287, 2024).
lung diseases (1 paper, 2023). "Recently, the role of angiopoietin-like 4 (ANGPTL4) expression level in lung diseases has noticeably attracted scholars’ attention." (PMID 37821811, 2023).
lymphoma (1 paper, 2023). A malignant (clonal) proliferation of B- lymphocytes or T- lymphocytes which involves the lymph nodes, bone marrow and/or extranodal sites. "No expression difference was found of ALDH2, ANGPTL4, BPGM, and PAM between lymphoma patients and control samples." (PMID 36755971, 2023).
membranoproliferative glomerulonephritis (1 paper, 2017). Inflammation of the glomeruli characterized by deposits at the intraglomerular mesangium, resulting in thickening of the glomerular basement membrane, activation of complement, and impaired kidney function secondary to damaged glomeruli. "Angptl4 staining was absent (as in control) in glomeruli from 4 MCD patients in relapse, 1 patient with membranoproliferative glomerulonephritis (MPGN) in relapse, and 1 of 6 with FSGS and heavy proteinuria." (PMID 28441404, 2017).
myocardial ischemia (1 paper, 2018). A disorder of cardiac function caused by insufficient blood flow to the muscle tissue of the heart. "Endothelial barrier function in the onset and Tongxinluo (TXL) protection of myocardial ischemia/reperfusion (I/R) injury, and TXL can induce the secretion of Angiopoietin-like 4 (Angptl4) in human cardiac microvascular endothelial cells during hypoxia/reoxygenation." (PMID 29912977, 2018).
Nocardia infection (1 paper, 2022). "In this study, ANGPTL4, which is involved in BBB integrity, was significantly upregulated, which indicated that this gene might play a critical role in the BBB destruction induced by Nocardia infection." (PMID 36352407, 2022).
oropharyngeal squamous cell carcinoma (1 paper, 2026). "The present study investigated the role of ANGPTL4 expression in oropharyngeal squamous cell carcinoma (OPSCC)." (PMID 42028751, 2026).
pancreatic disease (1 paper, 2025). "Additionally, future pharmacological studies focusing on ANGPTL4 inhibitors should be prioritized in pancreatic disease research." (PMID 39811640, 2025).
pneumococcal pneumonia (1 paper, 2019). A febrile disease caused by STREPTOCOCCUS PNEUMONIAE. "qPCR on fluorescence-activated cell sorter (FACS)-sorted major immune cell groups revealed that macrophages, neutrophils, natural killer (NK) cells, cytotoxic T cells, and B cells expressed ANGPTL4 at various levels during secondary pneumococcal pneumonia." (PMID 31164474, 2019).
Psoriasiform dermatitis (1 paper, 2022). A skin abnormality characterized by redness and irritation, with thick, red skin that displays flaky, silver-white patches (scales). "Compared with the IMQ group, the intradermal injection with recombinant ANGPTL4 protein significantly exacerbated the clinical phenotype of IMQ-induced psoriasiform dermatitis, which included redness, thickening, and scaling of the skin." (PMID 35860030, 2022). "To examine the ANGPTL4 expression profile in vivo, we established psoriasiform dermatitis animal models by inducing the skin of mice with IMQ." (PMID 35860030, 2022). "In our study, we found ANGPTL4 elevated in the skin and plasma of psoriasiform dermatitis models." (PMID 35860030, 2022).
purpura (1 paper, 2024). A small blood vessel hemorrhage into the skin and/or mucous membranes. "CCL19 (p-adj = 3.68 × 10− 2), osteopontin (p-adj = 3.68 × 10− 2) and ANGPTL4 (4.47 × 10− 2) were significantly higher in IgAV patients with necrotic purpura." (PMID 38610060, 2024). "In patients with more severe skin involvement, histologically presented as fibrinoid necrosis or with necrotic purpura we found higher ANGPTL4 levels than in nonnecrotic purpura." (PMID 38610060, 2024).
retinopathy of prematurity (1 paper, 2025). A bilateral retinopathy characterized by neovascularization, scarring, retinal detachment, and eventually blindness. "Beyond the diabetic context, ANGPTL4 is implicated in retinal ischemia and pathological neovascularization in retinopathy of prematurity (ROP)." (PMID 40723247, 2025).
sarcoidosis (1 paper, 2025). Sarcoidosis is a multisystemic disorder of unknown cause characterized by the formation of immune granulomas in involved organs. "Lastly, to mitigate bias from horizontal pleiotropy, we utilized “Phenoscanner” and “LDlink” to identify significant associations (P < 5 × 10–8) between rs660442 and rs2278236—cis-pQTLs for VEGFB and ANGPTL4, respectively—and phenotypes potentially linked to sarcoidosis." (PMID 39824903, 2025). "Additionally, three out of the four proteins preliminarily identified for sarcoidosis—VEGFB (coloc.abf-PPH4 = 0.907), LTBR (coloc.abf-PPH4 = 0.947), and ANGPTL4 (coloc.abf-PPH4 = 0.957)—received robust support by genetic colocalization analysis (PPH4 > 0.8) under standard priors and window (± 1 Mb)." (PMID 39824903, 2025).
Sciatica (1 paper, 2021). Pain in the lower back and hip radiating in the distribution of the sciatic nerve. "AZU1, BPI, TCF7L2, and WFIKKN1 were upregulated in sciatica patients, while ANGPTL4, CRP, EREG, FAM19A4, FGF1, LOC100129216, PLXNB1, RLN1, and RXFP2 were downregulated." (PMID 34925462, 2021).
serous papillary carcinomas (1 paper, 2015). "Expression of ANGPTL4, HER3 and HIF-1α was examined in 35 serous papillary carcinomas." (PMID 26205780, 2015).
ST Elevation Myocardial Infarction (1 paper, 2018). A myocardial infarction that produces elevation in the ST segments of the ECG. "It has been demonstrated that lower serum levels of Angptl4 is independently associated with no-reflow after successful PCI in ST-elevation myocardial infarction (STEMI) patients." (PMID 29912977, 2018).
stenosis (1 paper, 2021). "ANGPTL4 levels were obviously decreased in the anycoronary stenosis groups compared with the nonstenosis group." (PMID 34742313, 2021).
tongue cancer (1 paper, 2013). A malignant neoplasm affecting the tongue. "The elevated expression of ANGPTL4 was also proved to be correlated with poor prognosis in esophageal and tongue cancers." (PMID 23925665, 2013).
ulcerative colitis (1 paper, 2017). An inflammatory bowel disease involving the mucosal surface of the large intestine and rectum. "Next, a comparative gene expression analysis was performed between DSS-challenged ANGPTL4−/− and ANGPTL4+/+ mice and human ulcerative colitis (UC) colonoscopy samples." (PMID 28287161, 2017).
viral pneumonia (1 paper, 2026). Inflammation of the lung parenchyma that is caused by a viral infection. "In murine models of bacterial and viral pneumonia, Angptl4-ASO reduces inflammatory cell infiltration, preserves alveolar architecture, and improves host defence." (PMID 41869866, 2026).